RELN (reelin)
Diseases named in the same sentence as RELN in open-access papers (continued):
Sharing a sentence is not in itself a finding about the gene and the disease.
pancreatic cancer (9 papers, 2016 to 2025). "Likewise, RELN, which encodes a critical regulator of neuronal migration, is commonly hypermethylated and silenced in pancreatic cancer." (PMID 34439749, 2021). "Moreover, silenced Reelin promotes cancer cell motility and colony-formation ability in pancreatic cancer cells." (PMID 36568166, 2022). "Furthermore, low expression of RELN was significantly associated with worse survival outcomes, and siRNA knockdown of RELN in RELN-expressing pancreatic cancer cells enhanced cell motility, invasion, and colony formation." (PMID 34439749, 2021).
esophageal cancer (8 papers, 2012 to 2025). A primary or metastatic malignant neoplasm involving the esophagus. "Indeed, studies in hepatocellular or esophageal carcinoma cells have shown that enhanced cell migration in response to TGF-β1 is linked to the repression of RELN gene expression." (PMID 33477804, 2021). "Similar results were obtained in esophageal carcinoma cells, where RELN expression suppresses TGF-β1 induced migration." (PMID 34639052, 2021). "For example, Reelin is decreased in hepatocellular carcinoma, but increased in esophageal carcinoma." (PMID 34485127, 2021). "LIN2 and its target gene Reelin are obviously high‐expressed in human oesophageal cancer, and the upregulation of Reelin is caused by the overexpression of LIN2, which further participates in oesophageal cancer development by causing signalling pathway disorders." (PMID 40801824, 2025). "For example, in a human esophageal carcinoma cell line, RELN was related to TGF-β, which was related to metastasis, and knockdown of RELN increased the rate of cell migration." (PMID 34485127, 2021). "In contrast, upregulation of Reelin is observed in retinoblastoma, esophageal carcinoma, high-grade prostate cancer, multiple myeloma, and non-Hodgkin lymphoma." (PMID 34485127, 2021).
hepatocellular carcinoma (8 papers, 2012 to 2024). A malignant tumor that arises from hepatocytes. "RELN gene loss function in several tumors, including pancreatic, gastric, and BC, A high risk of recurrence of hepatocellular carcinoma is related to decreased expression of RELN, which was also associated with increased migratory ability, shorter survival, and a poor prognosis." (PMID 36358602, 2022). "Moreover, the decreased expression of RELN was associated with increased migratory ability, reduced survival and poor prognosis, reduced expression of Reelin is associated with high recurrence rate of hepatocellular carcinoma." (PMID 22393371, 2012). "In hepatocellular carcinoma, low levels of RELN correlate with increased recurrence." (PMID 38275881, 2024). "In addition, research has shown that blood Reelin levels are significantly elevated in patients with liver fibrosis or cirrhosis, and patients with hepatocellular carcinoma (HCC) have markedly higher concentrations of Reelin compared to patients with liver cirrhosis." (PMID 37246473, 2023). "For example, in hepatocellular carcinoma (HCC), relapse was more likely to happen when the expression of Reelin in tumor cells was high." (PMID 34485127, 2021).
Intellectual disability (8 papers, 2014 to 2025). "Mutations in RELN, as well as the reduction of Reelin expression, are associated with intellectual disability, learning, and memory deficits, and neurodegeneration." (PMID 39062513, 2024). "In these 2 patients, an NGS panel for genes associated with MCDs and intellectual disability revealed the c.2737C>T (p.Arg913Cys) missense substitution (R913C) in the RR2 of the RELN gene, which they both inherited from their apparently healthy, but unexamined, mother." (PMID 38980724, 2024). "Homozygous mutations in RELN, which encodes the secreted glycoprotein reelin, or the gene encoding its receptor VLDLR are responsible for severe cerebellar hypoplasia and intellectual disability in humans." (PMID 28165338, 2017).
memory impairment (8 papers, 2015 to 2025). "Overall, this study demonstrated that EE is effectively reversed the SI induced memory impairment by potentially regulating the molecules associated with the ITSN1-Reelin–AMPA receptor pathway to increase synaptic plasticity." (PMID 38241230, 2024). "Such deficits were indeed shown by recent experiments on reelin conditional knockout mice, and this is further corroborated by findings that an age-related decline in reelin levels in reelin-expressing alEC LII-neurons in monkeys associates with memory impairments." (PMID 37091586, 2023). "This Reelin/amyloid β-protein interaction correlates with memory impairments observed during AD evolution and in normal aging." (PMID 32438605, 2020). "In this line, the observed memory impairment in LTSC mice may be related to the observed lower level of Reelin expression." (PMID 38241230, 2024). "The relationship between PNS, the decrease of Reelin expression in CR neurons, and the anxious behavior accompanied with learning and memory impairments strongly place this study as a good model for investigating the origin and predisposition to acquired mental illnesses." (PMID 25679528, 2015). "Similar observations were made in aged rats and non-human primates exhibiting memory impairments, suggesting that a loss of Reelin may induce synaptic dysfunction during aging-related memory decline." (PMID 37891846, 2023). "This suggests a tentative clearance from the glial cells of the small Reelin aggregates, while the uncleared larger deposits might affect the normal function and survival of afferent neurons, leading to neurodegeneration in the hippocampus and subsequent memory impairments." (PMID 37891846, 2023).
mental disorder (8 papers, 2010 to 2023). A disease that has its basis in the disruption of mental process. "Collectively, our approach should be useful for studying reelin function and evaluating mental disorder susceptibility, focusing on individual human neuronal migration." (PMID 30022058, 2018). "Our study, focusing on the directionality of individual cell migration, provides a foundation for the elucidation of reelin function in neural development and may contribute to novel therapeutic strategies for mitigating mental disorder susceptibility." (PMID 30022058, 2018). "There is the possibility therefore that alterations in serotonin transporter clustering in blood lymphocytes associated with a decrease in reelin expression may be operative in some cardiovascular or immune system alterations showing comorbidity with these mental disorders." (PMID 20414372, 2010). "Because reelin signaling through ApoER2 in adult brains modulates synaptic plasticity and memory formation, a defective reelin signaling pathway may contribute to the pathogenesis of adult mental disorders." (PMID 25405877, 2014). "Thus, reelin signaling and ER quality control may be related to the pathogenesis of adult mental disorders, as seen in the reeler mutant–like cerebral malformation in the homozygous mutant BiP neonates." (PMID 25405877, 2014). "The results of the present report also invite to consider the actions of plasma reelin actions in SERT clustering in lymphocytes as a possible factor of importance in understanding the comorbidities between some immune and/or vascular systems alterations and these mental disorders." (PMID 20414372, 2010).
Stroke (8 papers, 2014 to 2025). Sudden impairment of blood flow to a part of the brain due to occlusion or rupture of an artery to the brain. "In this regard, reelin‐deficient mice exhibited impaired neurogenesis in SGZ and deteriorated infarction volume post‐stroke." (PMID 35715988, 2022). "Accordingly, mNSS scores exhibited higher functional recovery in stroke mice that received Reelin‐loaded PLGA‐PEG micelles compared to the other groups." (PMID 35111956, 2022). "Based on our data, the application of Reelin alone or in combination with PLGA‐PEG micelles can reduce cavity size in comparison with the PBS + Stroke group (p < 0.05)." (PMID 35111956, 2022). "Here, we evaluated neurogenesis and functional behavior efficiency by using a cocktail of PLGA‐PEG, Reelin, and NSCs in the photothrombotic stroke in the model of the mouse." (PMID 35111956, 2022). "In contrast, another study reported that upregulation of miR-200c after stroke promoted neuronal cell death through inhibiting expression of its target protein (reelin) that plays a role in synaptogenesis and neuronal migration." (PMID 34131232, 2021). "At day 14 after stroke, a trend of enhanced expression of rat reelin and GPx-4 mRNA was detected in sham and cbMNC-treated animals compared with the PBS group." (PMID 24690461, 2014). "These are common risk factors for cardiovascular disease, pulmonary hypertension, and stroke, of which Reelin lowering could predictably affect in a favorable manner." (PMID 38607022, 2024). "This study aimed to test the regenerative potential of polylactic‐co‐glycolic acid‐polyethylene glycol (PLGA‐PEG) micelle biomaterial enriched with Reelin and embryonic NSCs on photothrombotic stroke model of mice to gain appropriate methods in tissue engineering." (PMID 35111956, 2022). "Interestingly, we found that the reduction of cavity size was at the maximum levels in stroke mice that received Reelin‐loaded PLGA‐PEG micelles (p < 0.05)." (PMID 35111956, 2022). "Interestingly, this study also showed that ischemia causes the upregulation of the microRNA miR-200c, which targets and suppresses Reelin gene expression, suggesting that this could contribute to stroke-induced injury." (PMID 32610618, 2020). "Although it is unknown whether administration of exogenous thyroid hormone in stroke patients improves outcomes, administration of T3 resulted in increased mRNA expression of reelin and brain-derived neurotrophic factor in rats, both of which are important in nervous system regeneration." (PMID 26157487, 2015). "Data showed that the administration of Reelin, PLG‐PEG, and Reelin‐load PLGA‐PEG micelles with NSCs can alter the levels of astrocytic gliosis and local angiogenesis in the ischemic areas compared to the Stroke group received PBS." (PMID 35111956, 2022). "Of note, the administration of Reelin or PLGA‐PEG in combination with NSCs can significantly reduce the number of recruited astrocytes (GFAP+ cells) in the periphery and inside the necrotic sites compared to the control stroke group." (PMID 35111956, 2022). "At 2 weeks after stroke, insignificant differences in the expression of reelin and EGF mRNA between the PBS, sham, and cell groups could indicate that reelin-mediated migration of progenitors and EGF-mediated recovery after stroke is time dependent." (PMID 24690461, 2014).
Cerebellar hypoplasia (7 papers, 2015 to 2024). Cerebellar hypoplasia is a descriptive term implying a cerebellum with a reduced volume, but a normal shape and is stable over time. "Recessive RELN mutations have been associated with severe cerebellar hypoplasia in humans." (PMID 28165338, 2017).
myeloma (7 papers, 2016 to 2025). "For example, activated FAK/Syk/Akt/mTOR and STAT3 pathways are known to underlie Reelin-driven cancer cell growth and metabolic reprogramming, including glycolysis in myeloma cells." (PMID 35379785, 2022). "In this study, we demonstrate that Reelin is negatively associated with myeloma prognosis and plays an important role in the regulation of cancer cell growth both in vitro and in vivo." (PMID 28345605, 2017). "Taken together, the current study and our previous one demonstrate that high expression of Reelin in myeloma patients is associated with tumor progression and poor patient outcome." (PMID 28345605, 2017). "The expression of reelin in multiple myeloma (MM) cells and its association with cell adhesion and survival were investigated." (PMID 26848618, 2016). "We find that Reelin expression is negatively associated with myeloma prognosis." (PMID 28345605, 2017). "According to the significant role of Reelin in tumor progression, some studies showed that upregulated Reelin was found to be correlated with proliferation of cancer cells in multiple myeloma." (PMID 34485127, 2021). "Together, our results demonstrate the critical contributions of Reelin to myeloma growth and metabolism." (PMID 28345605, 2017). "Our investigation on multiple myeloma cell lines indicates that Reelin-induced activation of integrin β110 and its downstream FAK/Syk results in the phosphorylation of both PI3K/Akt/mTOR and STAT3, providing combinatorial cues for myeloma cell proliferation." (PMID 28345605, 2017). "It is thus likely that the contribution of Reelin in myeloma chemoresistance is at least partially through enhanced glucose metabolism." (PMID 28345605, 2017). "Together with the fact that reduced cell proliferation was found in myeloma cells with Reelin knockdown, these suggest that Reelin has an autocrine effect and is required to be released from the cells to promote integrin β1 activation and cell growth." (PMID 28345605, 2017). "It provides an opportunity for myeloma therapeutic intervention by inhibiting Reelin and its integrin pathway." (PMID 28345605, 2017). "The treatment with Syk inhibitor abolished the elevated glycolysis in Reelin overexpressing cells, suggesting a critical role of Syk in Reelin-induced myeloma cell glycolysis." (PMID 28345605, 2017). "Reelin’s role in myeloma cell glycolysis was further supported by the clinical data from GSE24080 as high RELN-expressing patients also revealed high levels of HIF1α, PDK1, and LDHA expression." (PMID 28345605, 2017). "Together, these results indicate that Reelin-mediated cell proliferation is at least partially due to its role in promoting glycolysis in myeloma cells." (PMID 28345605, 2017). "The activation of VLDLR/Dab1-independent integrin β1 signaling pathway is involved in Reelin-mediated myeloma cell adhesion and survival." (PMID 28345605, 2017). "A decrease in G0/G1 phase and an increase in S-phase were found in Reelin-overexpressing cells, suggesting that Reelin promotes myeloma cell cycle progression from G1 to S phase." (PMID 28345605, 2017). "It presents an opportunity for myeloma therapeutic intervention by inhibiting Reelin and its signaling pathways." (PMID 28345605, 2017). "We examined the expression of Reelin in a large cohort of multiple myeloma patients recorded in Gene Expression Omnibus (GEO) database and used over-expression and siRNA knockdown of Reelin to investigate the role of Reelin in myeloma cell growth." (PMID 28345605, 2017). "The FAK/Syk/Akt/mTOR and STAT3 signaling pathways activated by Reelin significantly contribute to the increase in myeloma cell proliferation and glycolysis." (PMID 28345605, 2017). "Here we show for the first time that Reelin plays an important role in the regulation of myeloma cell proliferation and glucose metabolism." (PMID 28345605, 2017).
myeloma (continued). "In patients, various amounts of RELN was found in CD138+ myeloma cells and a hierarchical cluster analysis with Ward's method was used to analyze the relative expression fold of RELN (compared with the GAPDH control)." (PMID 26848618, 2016). "We further explored whether Reelin depletion alters myeloma cell proliferation, apoptosis, and invasiveness, thus influence OC and OB activity, and rebalance osteolysis and osteogenesis." (PMID 34433809, 2021). "Inconclusion, our results suggested that Reelin exerted important impacts on myeloma development through rebalancing osteolysis and osteogenesis, thus might be a potential therapeutic target for MM." (PMID 34433809, 2021). "Reelin exerted important impacts on myeloma development through rebalancing osteolysis and osteogenesis, thus might be a potential therapeutic target for MM." (PMID 34433809, 2021). "Our data suggested that inhibiting Reelin expression in myeloma cells could suppress tumor growth and also restrain its invasive ability." (PMID 34433809, 2021). "Therefore, a delicate balance among osteoclast, osteoblast, and myeloma cells was regulated and maintained by Reelin depletion." (PMID 34433809, 2021). "Moreover, as a previous study showed, high-expressed Reelin was negatively associated with PFS and OS in multiple myeloma." (PMID 34485127, 2021). "Reelin promotes myeloma cell proliferation in vitro as well as in vivo." (PMID 28345605, 2017). "Thus, the decrease in p21, increase in Cyclin D1, and increase in Rb phosphorylation all indicate that Reelin facilitates myeloma cell proliferation by regulating key proteins involved in G1/S transition." (PMID 28345605, 2017). "Since myeloma cells are neoplastic plasma cells which make monoclonal immunoglobulins, we detected the serum IgA levels at day 14, 28, and 42 to explore whether Reelin can inhibit the production of this monoclonal protein, thus suppressing the pathologic effects of MM." (PMID 34433809, 2021). "Whether integrin signaling pathway activated by Reelin is associated with metabolic reprogramming in myeloma cells is not known." (PMID 28345605, 2017). "In addition, the blockage of Reelin secretion by Brefeldin A could diminish Reelin-induced integrin β1 activation in myeloma cells." (PMID 28345605, 2017). "It indicates that Reelin may serve as an excellent therapeutic target for myeloma treatment." (PMID 28345605, 2017). "The current study revealed that Reelin/FAK/Syk/Akt and STAT3 pathways in myeloma cells promoted HIF1α expression and cell glycolysis." (PMID 28345605, 2017). "The knockdown of STAT3 and suppression of PI3K each significantly decreased but did not completely abolish Reelin-mediated Cyclin D1 upreguation and myeloma cell proliferation." (PMID 28345605, 2017). "Thus, Reelin-induced phosphorylation of Akt and STAT3 may act in concerto to promote myeloma cell growth." (PMID 28345605, 2017). "In this study, we show that reelin produced by MM cells promotes the adhesion of tumor cells to fibronectin via activation of integrin β1-FAK pathway and the subsequent activation of Akt and STAT3 signaling molecules, eventually facilitating the survival and drug resistance of myeloma cells." (PMID 26848618, 2016).
amyloid (6 papers, 2016 to 2025). "Different immunomodulatory strategies are currently under investigation in preclinical AD models for Reelin potential therapeutic impact in reducing amyloidosis and regulating neuroinflammation." (PMID 40867631, 2025). "Given the progressive memory decline seen in AD patients, it is possible that the sequestering of Reelin by the amyloid plaques can alter its normal regulation via cleavage mechanisms and its normal enhancement of learning and memory." (PMID 27065802, 2016).